SULT2B1 (sulfotransferase family 2B member 1)
Description:
Sulfotransferase that utilizes 3'-phospho-5'-adenylyl sulfate (PAPS) as sulfonate donor to catalyze the sulfate conjugation. Responsible for the sulfation of cholesterol. Catalyzes sulfation of the 3beta-hydroxyl groups of steroids, such as, pregnenolone and dehydroepiandrosterone (DHEA). Preferentially sulfonates cholesterol, while it also has significant activity with pregnenolone and DHEA. Plays a role in epidermal cholesterol metabolism and in the regulation of epidermal proliferation and differentiation. [Isoform 2]: Sulfonates pregnenolone but not cholesterol.
Synonyms: HSST2; ARCI14
Tractability: Small molecule: a structure with a bound ligand is known; it has a high-quality binding pocket.
Target class: Enzyme; Transferase
Safety:
Unwanted effects reported when the protein is acted on. In parentheses: how it was acted on, where the effect was seen, and who reports it.
cardiotoxicity (source: ClinPGx)
fever (source: ClinPGx)
Gene: Protein-coding gene on chromosome 19 (48,552,172 to 48,599,425, forward strand). Ensembl gene ENSG00000088002.
Subcellular location: Cytoplasm, cytosol; Microsome; Nucleus
Subcellular location (Human Protein Atlas): Vesicles; Cytosol
Pathways (Reactome):
Metabolism: Cytosolic sulfonation of small molecules
Gene Ontology:
Molecular function: alcohol sulfotransferase activity; cholesterol binding; cholesterol sulfotransferase activity; nucleic acid binding; protein binding; small molecule binding; steroid hormone binding; steroid sulfotransferase activity; sulfotransferase activity
Biological process: 3'-phosphoadenosine 5'-phosphosulfate metabolic process; cholesterol metabolic process; negative regulation of cell population proliferation; positive regulation of epidermal cell differentiation; steroid metabolic process; sulfation; sulfur compound metabolic process
Cellular component: cytosol; extracellular exosome; nucleus; cytoplasm
Genetic constraint (gnomAD): Loss-of-function variants: 17 observed, 29.92 expected, observed/expected ratio (o/e) 0.57, 90% interval 0.39 to 0.85. The upper end of that interval is the gene's LOEUF score, 0.85, which puts it in group 3 of 6, group 1 being the genes least tolerant of losing a copy. Missense variants: 500 observed, 489.4 expected, observed/expected ratio (o/e) 1.02, 90% interval 0.95 to 1.1. Synonymous variants: 186 observed, 190.36 expected, observed/expected ratio (o/e) 0.98, 90% interval 0.87 to 1.1.
Homologues: Orthologues: chimpanzee SULT2B1 (98% identical), macaque SULT2B1 (95% identical), dog SULT2B1 (77% identical), pig SULT2B1 (76% identical), rabbit SULT2B1 (71% identical), guinea pig SULT2B1 (71% identical), rat Sult2b1 (70% identical), mouse Sult2b1 (69% identical), tropical clawed frog XB5850668 (40% identical), tropical clawed frog sult2a1 (36% identical), Drosophila melanogaster St3 (23% identical), tropical clawed frog XB986081 (22% identical), and 2 more. Paralogues in human: SULT2A1 (38% identical), SULT1A3 (30% identical), SULT1A4 (30% identical), SULT1B1 (29% identical), SULT1A1 (29% identical), SULT1A2 (28% identical), SULT1C4 (28% identical), SULT1C2 (28% identical), SULT1E1 (27% identical), SULT1C3 (27% identical), SULT4A1 (25% identical), SULT6B1 (24% identical).
Diseases named in the same sentence as SULT2B1 in open-access papers:
SULT2B1 is named in the same sentence as 55 diseases in open-access papers, as found by Europe PMC text mining. Sharing a sentence is not in itself a finding about the gene and the disease. The quoted sentences say what the papers report.
colon cancer (5 papers, 2021 to 2024). "Hence, this research was designed to explore the mechanism underlying the OLR1/c-MYC/SULT2B1 axis in the regulation of glycolytic metabolism, to affect colon cancer cell proliferation and chemoresistance." (PMID 34921134, 2021). "The study also showed that SULT2B1 facilitates lipid metabolism and promotes colon cancer cell metastasis by interacting directly with stearoyl-CoA desaturase (SCD1), which is involved in lipid metabolism." (PMID 39280099, 2024). "When the clinical course was compared between colon cancer patients with high and low SULT2B1 expression, SULT2B1-high patients showed poor prognosis." (PMID 35094065, 2022). "Meanwhile, MTS assay, clone formation assay, and RT-qPCR manifested that overexpression of SULT2B1 negated the repressive effect of c-MYC knockdown on colon cancer cell proliferation." (PMID 34921134, 2021). "The obtained data in our research manifested that knockdown of c-MYC depressed the proliferation and chemoresistance of colon cancer cells by diminishing glycolytic metabolism via SULT2B1 downregulation." (PMID 34921134, 2021). "Overexpression of SULT2B1 neutralized the sensitization effect of colon cancer cells to chemotherapeutic drugs induced by c-MYC knockdown." (PMID 34921134, 2021). "The results of immunohistochemical staining exhibited that compared with the adjacent normal tissues, SULT2B1 was highly expressed in colon cancer tissues and mainly located in the cytoplasm of colon cancer tissues." (PMID 34921134, 2021). "The MTS assay, clone formation assay, and Ki67 expression also manifested that overexpression of SULT2B1 annulled the suppression of the proliferation of colon cancer cells triggered by OLR1 knockdown." (PMID 34921134, 2021). "Furthermore, SULT2B1 expression level has been suggested to be used as an oncogenic marker for colon cancer stage and prognosis." (PMID 39280099, 2024). "SULT2B1 promoted lipid metabolism and metastasis of colon cancer." (PMID 38372484, 2024). "SMC1A transcriptionally upregulated the expression of SULT2B1 in colon cancer." (PMID 38372484, 2024). "In short, knockdown of c-MYC could decline SULT2B1 expression to curtailed glycolytic metabolism, thereby inhibiting the proliferation and chemoresistance of colon cancer cells." (PMID 34921134, 2021). "All in all, knockdown of OLR1 might downregulate SULT2B1 to repress glycolytic metabolism, thereby dampening the proliferation and chemoresistance of colon cancer cells." (PMID 34921134, 2021). "In order to further explore whether OLR1/c-MYC/SULT2B1 axis could also modulate the growth and chemoresistance of colon cancer cells in vivo, a subcutaneous tumor transplantation experiment was implemented in nude mice." (PMID 34921134, 2021). "The levels of OLR1, c-MYC, and SULT2B1 were upregulated in colon cancer tissues and cells." (PMID 34921134, 2021). "Moreover, knockdown of OLR1, c-MYC, or SULT2B1 weakened glycolytic metabolism, proliferation, and chemoresistance of colon cancer cells." (PMID 34921134, 2021). "Mechanistically, OLR1 increased c-MYC expression to upregulate SULT2B1 in colon cancer cells." (PMID 34921134, 2021). "Furthermore, another study has reported that SULT2B1 is highly expressed in chemoresistance colon cancer and radio-resistance tissues, which promotes cell proliferation and chemoresistance in colon cancer through its involvement in oncogenic signaling involving the OLR1/c-MYC/SULT2B1 axis." (PMID 39280099, 2024). "Furthermore, the colon cancer cells were infected with lentivirus to confirm that c-MYC could orchestrate SULT2B1 expression." (PMID 34921134, 2021). "SULT2B1 expression was diminished by downregulating c-MYC, thereby restraining glycolytic metabolism to inhibit colon cancer cell proliferation and chemoresistance under condition of knockdown of OLR1." (PMID 37337170, 2023).
colon cancer (continued). "Colon cancer tissues and LoVo cells were attained, where OLR1, c-MYC, and SULT2B1 expression was detected by immunohistochemistry, RT-qPCR, and western blot analysis." (PMID 34921134, 2021). "Therefore, we believed that SULT2B1 might be a key downstream gene of c-MYC in colon cancer." (PMID 34921134, 2021). "As reflected by RT-qPCR, increased c-MYC and SULT2B1 expression in LoVo colon cancer cells was noticed following c-MYC overexpression, which was opposite after silencing c-MYC, indicating that c-MYC could upregulate SULT2B1." (PMID 34921134, 2021). "Taken together, SULT2B1 was highly expressed in colon cancer cells, and knockdown of c-MYC could disturb SULT2B1 expression and inhibit the glycolytic metabolism of colon cancer cells." (PMID 34921134, 2021). "Generally speaking, knockdown of OLR1 might inhibit the tumorigenicity and chemoresistance of colon cancer cells in nude mice by downregulating c-MYC and SULT2B1." (PMID 34921134, 2021). "Conclusively, knockdown of OLR1 might diminish SULT2B1 expression by downregulating c-MYC, thereby restraining glycolytic metabolism to inhibit colon cancer cell proliferation and chemoresistance." (PMID 34921134, 2021). "In order to further explore whether c-MYC manipulated glycolytic metabolism through SULT2B1 to affect the proliferation and chemoresistance of colon cancer cells, we successfully constructed a cell line with c-MYC knockdown and SULT2B1 overexpression." (PMID 34921134, 2021).
colitis (4 papers, 2016 to 2023). Inflammation of the colon. "While dextran sodium sulfate (DSS)-induced colitis was exacerbated in Sult2b1-deficient mice with increased prevalence of neutrophils, the elimination of either neutrophils or intestinal bacteria in Sult2b1-deficient mice attenuated disease development." (PMID 37006281, 2023). "Further, we investigated the functional role of CS during mucosal injury using Sult2b1-deficient (Sult2b1−/−) mice under dextran sodium sulfate (DSS)-induced colitis and indomethacin (IND)-induced SI ulcer formation." (PMID 37006281, 2023). "Importantly, we found in this study that the degree of weight loss during DSS-induced colitis was comparable between Sult2b1+/+ and Sult2b1−/− mice when Dock2 was genetically deleted." (PMID 37006281, 2023). "A recent study has reported that IEC-specific Sult2b1 deletion mice (Sult2b1f/f Villin-Cre mice) develop severe DSS-induced colitis, compared with the control Sult2b1f/f mice." (PMID 37006281, 2023). "By bacterial depletion using oral antibiotics prior to the 1.5% DSS challenge, the clinical signs of colitis, such as body weight loss, DAI score, and colon length shortening, were recovered in Sult2b1−/− mice to the levels similar to those in Sult2b1+/+ mice." (PMID 37006281, 2023). "On day 6 of the 2.5% DDS-induced colitis mouse model, SULT2B1 and CS levels in colonic epithelium were decreased due to severe colonic epithelium loss." (PMID 35908039, 2022). "Next, we monitored the dynamic changes in SULT2B1 expression in the colonic tissues of mice with DSS-induced colitis." (PMID 35908039, 2022). "In the mice recovered from 3-day 2.5% DSS challenge or mice with 0.5% DSS-induced colitis, the protein level of SULT2B1 in the colonic tissues was increased compared to that in controls." (PMID 35908039, 2022). "To determine the molecular basis of SULT2B1 and CS in regulating colonic colitis, we performed RNA-seq using inflamed colon samples from Sult2b1f/f and Sult2b1∆IEC mice challenged with 2.5% DSS." (PMID 35908039, 2022). "Specific deletion of the Sult2b1 gene in the intestinal epithelial cells aggravates dextran sulfate sodium-induced colitis; however, dietary supplementation with cholesterol sulfate ameliorates this effect in acute and chronic ulcerative colitis in mice." (PMID 35908039, 2022). "CS deficiency caused by IEC-specific deletion of Sult2b1 aggravated DSS-induced colitis in mice, while dietary supplementation with CS ameliorated colitis in acute and chronic UC mice." (PMID 35908039, 2022). "Based on these findings, we speculated that even short exposures to and/or low concentrations of DSS would induce severe colitis in Sult2b1+/− and Sult2b1−/− mice." (PMID 37006281, 2023). "To examine whether CS affects gut inflammation, we compared the severity of DSS-induced colitis among Sult2b1+/+, Sult2b1+/−, and Sult2b1−/− mice." (PMID 37006281, 2023). "The decrease in SULT2B1 and CS might be due to the notably high amount of colonic epithelial cell death and detachment observed in this acute and severe mouse colitis model." (PMID 35908039, 2022). "Therefore, the increased levels of PBLD, FAM3D, KRT8, SULT2B1, GPA33, DEPTOR, and decreased expression of ACSL4, IFITM1 and HSD11B1 caused by mEVs has been demonstrated to attenuate colitis, implying that consumption of mEVs has the potential to improve intestinal health." (PMID 35893911, 2022). "We found that, irrespectively of Sult2b1 expression, the percentage of CD45+ cells in the total live cells gradually increased in the colon during the progression of colitis; however, the percentages of CD45+ cells were unchanged among these mice." (PMID 37006281, 2023). "When Sult2b1 was genetically deleted, DSS-induced colitis and NSAID-induced SI ulcers were markedly exacerbated, compared with the case of Sult2b1+/+ mice." (PMID 37006281, 2023).
colitis (continued). "To comprehensively analyze the immune cell profiles in the colon from Sult2b1+/+ and Sult2b1−/− mice during DSS-induced colitis, we performed high-dimensional phenotyping of intraepithelial and lamina propria immune cells using cytometry by time-of-flight (CyTOF)." (PMID 37006281, 2023). "However, in the acute and severe mouse colitis model induced using 2.5% DSS treatment for six days, SULT2B1 expression was found to be decreased in colonic epithelia compared to that in controls." (PMID 35908039, 2022).
psoriasis (4 papers, 2015 to 2025). An autoimmune condition characterized by red, well-delineated plaques with silvery scales that are usually on the extensor surfaces and scalp. "Here, IFNγ and TNFα, the key Th1 cytokines implicated in psoriasis pathogenesis, induced SULT2B1 expression in human epidermal KCs, whereas Th2 and Th17 cytokines did not alter SULT2B1 expression." (PMID 41181147, 2025). "Therefore, the loss of ceramides and sulfated cholesterol owing to deficiencies in CerS2, CerS3 and SULT2B1 is implicated in not only the reduction of barrier function but also the pathogenesis of skin diseases such as psoriasis and ichthyosis." (PMID 40637102, 2025). "SULT2B1 expression levels are higher in the skin of patients with psoriasis than in that of healthy subjects." (PMID 41181147, 2025). "Within the broader landscape of psoriasis biology, SULT2B1 is positioned as a key metabolic enzyme forming a complex epithelial-immune network." (PMID 41181147, 2025). "Using a murine model of psoriasis-like dermatitis induced by topical IMQ, we found that the loss of SULT2B1 was associated with exacerbated skin inflammation and infiltration of neutrophils, which are central to psoriatic pathology." (PMID 41181147, 2025). "Genes controlling abnormal keratinocyte differentiation and epidermal barrier function (CYP4F22, SULT2B1) were up-regulated in psoriasis." (PMID 26901218, 2016). "However, if only the SULT2B1-CS-DOCK2 axis is affected in psoriasis-like dermatitis, psoriatic phenotypes in Sult2b1−/−Dock2−/− mice would be expected to decrease to WT levels." (PMID 41181147, 2025). "Overall, our results raise the possibility that SULT2B1 plays an important role in cutaneous inflammation and could serve as a useful indicator or potential target in psoriasis." (PMID 41181147, 2025). "Of the most psoriasis-specific DEGPs, the majority were induced by IL-17A (e.g., FERMT1, GLUL, SULT2B1); in contrast, the most non-specific DEGPs were not disproportionately induced by IL-17A and several were repressed (e.g., AKR1B10, RNF213, ISG15)." (PMID 26251673, 2015).
atherosclerosis (3 papers, 2024). A disease characterized by the build-up of fatty material and calcium deposition in the arterial wall resulting in partial or complete occlusion of the arterial lumen. "In fact, the knockdown of SULT2B1 in animal models was suggested to promote atherosclerosis remission and reduce inflammatory mediator levels." (PMID 39280099, 2024). "Hangyu Pan found that inhibition of SULT2B1, reduced macrophage inflammatory response, stabilized plaque, and delayed the progression of atherosclerosis." (PMID 39525632, 2024). "SULT2B1 can indicate inflammatory status, providing insights into potential treatment strategies for atherosclerosis." (PMID 39610928, 2024). "Additionally, a recent study has reported that SULT2B1 expression is elevated with the progression of atherosclerosis." (PMID 39280099, 2024).
esophageal squamous cell carcinoma (3 papers, 2019 to 2024). Esophageal squamous cell carcinoma (ESCC) is a type of esophageal carcinoma (EC) that can affect any part of the esophagus, but is usually located in the upper or middle third. "Genetic analysis of esophageal squamous cell carcinoma (ESCC) reveals that the SULT2B1 rs4149455 intronic variant and rs1052131 synonymous variant correlate with reduced cancer risks." (PMID 39280099, 2024). "SULT2B1 can inhibit the proliferation of esophageal squamous cell carcinoma (ESCC) cells, and the hypermethylation of its promoter can promote the progression of esophageal tumor by downregulating PER1." (PMID 35628460, 2022).
gastric cancer (3 papers, 2019 to 2024). A primary or metastatic malignant neoplasm involving the stomach. "The SULT2B1 expression level was also correlated with gastric cancer stage and proposed to be used as an independent biomarker for gastric cancer prognosis." (PMID 39280099, 2024). "Kaplan–Meier survival analysis indicated that patients with high expression of SULT2B1 in gastric cancer tissue had a lower survival probability than other patients." (PMID 31757214, 2019). "Therefore, the role of SULT2B1 in the development of gastric cancer is complicated and requires further investigation." (PMID 31757214, 2019). "Although SULT2B1 might promote normal epithelial cell proliferation via the PI3K/AKT signaling pathway, the PI3K/AKT signaling pathway is still involved in gastric cancer progression." (PMID 31757214, 2019).
ovarian carcinoma (3 papers, 2018 to 2025). A malignant neoplasm originating from the surface ovarian epithelium. "Moreover, overexpression of SULT2B1 has been correlated with poor prognosis in endometrial, cervical, and ovarian cancers, thereby representing a potential link that merits future evaluation regarding the coexistence of adenomyosis with ovarian cancer, as implicated in the literature." (PMID 41374450, 2025). "Downregulation of SULT2B1 in ovarian cancer cell lines reduces cell proliferation, migration, and invasion by binding to annexin A9 (ANXA9) and regulates its expression." (PMID 39280099, 2024). "Similarly, SULT2B1 is also reported to be expressed at a high level in endometrial cancer, cervical cancer, and ovarian cancer, which negatively impacts prognosis." (PMID 39280099, 2024).
prostate carcinoma (3 papers, 2015 to 2024). A carcinoma that arises from epithelial cells of the prostate gland. "SULT2B1 intron variants (rs12460535, rs2665582, and rs10426628) were found to be correlated with prostate cancer progression and overall survival rate." (PMID 39280099, 2024). "The study suggested that SULT2B1 (rs10426628) lowers the risk of prostate cancer progression by reducing the circulating steroid hormones via forming less active sulfated metabolites." (PMID 39280099, 2024). "Germline polymorphisms in the estradiol-metabolism related enzyme SULT2B1 have been associated to prostate cancer risk, and its expression has been shown to be reduced in this type of tumor." (PMID 26620706, 2015).
breast carcinoma (2 papers, 2010 to 2024). "On the other hand, in breast cancer, SULT2B1 expression was reported to be upregulated in both estrogen receptor a (ERa) positive and negative breast cancer tissues, with a higher level in ER-positive tumors." (PMID 39280099, 2024). "Consistent with the pathway-based associations, the gene-based associations are generally more significant in sporadic postmenopausal patient samples than in the whole breast cancer sample (except SULT2B1)." (PMID 20617168, 2010). "We also observed suggestive association for UGT2B11 in breast and endometrial cancer as well as for HSD11B1, SULT2A1 and SULT2B1 in breast cancer." (PMID 20617168, 2010).